CD28 (CD28 molecule)
Diseases named in the same sentence as CD28 in open-access papers (continued):
Sharing a sentence is not in itself a finding about the gene and the disease.
chordoma (1 paper, 2021). Chordomas are rare malignant tumors arising from embryonic remnants of the notochord in axial skeleton. "Moreover, future works are needed to explore the expression pattern and biological functions of the respective ligands of PD-L1 and HHLA2 (namely, PD-1 and CD28) in chordoma tissues." (PMID 35145510, 2021).
chorioamnionitis (1 paper, 2016). A morphologic finding indicating inflammation of the fetal sac membranes. "Considering that lung inflammation may be a constant problem in preterm infants due to infection, chorioamnionitis, or ventilation, we simulated a simultaneous inflammatory trigger in vitro by activating CD4+ T cells using CD3/CD28 antibodies during exposure to surfactant." (PMID 27077658, 2016).
chronic granulomatous disease (1 paper, 2025). Chronic granulomatous disease (CGD) is a rare primary immunodeficiency, mainly affecting phagocytes, which is characterized by an increased susceptibility to severe and recurrent bacterial and fungal infections, along with the development of granulomas. "Finally, we and others observed suppressed murine Treg expansion in Ncf1*/* mutant chronic granulomatous disease (CGD) mice with anti-CD3ε/CD28 stimulation, which was reestablished during Treg polarization with robust TGFβ signaling." (PMID 41300507, 2025).
chronic GvHD (1 paper, 2017). "However, for CD28’s inhibitory counter player CTLA-4 it has been shown that the 49G polymorphism, leading to comparatively weak B7-binding, is associated with enhanced T cell responses in vitro and a higher risk to develop chronic GvHD in vivo." (PMID 28690612, 2017).
chronic hepatitis B (1 paper, 2014). "The aim of this study was to evaluate the change of costimulatory molecule CD28 on circulating CD8+ T cells in chronic hepatitis B patients (CHB)." (PMID 25013781, 2014). "The frequency of CD28+CD8+ T cells and especially the balance between CD8+CD28+ and CD8+CD28− T cells are important in many diseases, including chronic hepatitis B (CHB)." (PMID 25013781, 2014).
chronic hepatitis C (1 paper, 2012). "To confirm the regulatory function of our 7 Treg clones from chronic hepatitis C, we performed co-culture assays to determine their inhibitory capacity against autologous TH1 and TH2 clones after anti-CD3/anti-CD28 stimulation." (PMID 22848715, 2012). "To determine the direct influence of ribavirin on differentially polarized CD4+ T cells from chronic hepatitis C, we stimulated our Treg, TH1 and TH2 clones with anti-CD3/anti-CD28 in the presence of variable concentrations of ribavirin and measured their proliferation and cytokine responses." (PMID 22848715, 2012).
Cluster headache (1 paper, 2017). A type of headache characterized by repeated attacks of unilateral pain lasting 15 to 180 minutes and associated with local autonomic signs. "These analyses suggest that inter- and intracellular signalling pathways involving brain-related molecules (e.g. GABA and ion channels) and inflammation-related molecules (e.g. CD28 and interleukin-4 (IL-4)), metabolism and oxidation might be involved in cluster headache." (PMID 28074859, 2017).
cognitive decline (1 paper, 2022). "In AD patients, the correlation analysis showed an association between the decline in CD28 + T cells and the increase in CTLA-4 + T cells with cognitive decline, measured by the mini-mental state examination (MMSE), tau proteins and Amyloid-β, important AD biomarkers in cerebrospinal fluid (CSF)." (PMID 34427746, 2022).
colorectal adenocarcinoma (1 paper, 2020). The most common type of colorectal carcinoma. "To test this hypothesis, we co-cultured TDO-expressing SW48 human colorectal adenocarcinoma cells with human CD8+ T cells stimulated to proliferate by anti-CD3/CD28 beads." (PMID 32637034, 2020).
cyst (1 paper, 2024). A sac-like closed membranous structure that may be empty or contain fluid or amorphous material. "The results of the present study may also suggest that, in the presence of CD28 expression, the increased expression of ICOS in WT CD8+ T cells, as detected in our recent study, could enhance their anti-cyst effector activity, allowing them to eliminate T. gondii cysts." (PMID 39682747, 2024).
cystitis (1 paper, 2024). Inflammation of the urinary bladder. "In our patient, we observed an increase of CD8+ CD28+ T cells in peripheral blood during the onset of cystitis (22.4%–24%, normal range 8.6%–15.5%), which may contribute to cystitis." (PMID 39034999, 2024).
diabetic kidney disease (1 paper, 2021). Progressive kidney disorder caused by vascular damage to the glomerular capillaries, in patients with diabetes mellitus. "Few studies have illuminated the genetic role of T cell costimulatory molecule CD28/CD80/CTLA4 variants in diabetic kidney disease (DKD) susceptibility." (PMID 33958973, 2021).
dry eyes (1 paper, 2021). "Abatacept, a CTLA4-Iginitially developed as a competitive inhibitor of CD28/B7 pathway that acts against CD4 + T-cells, better impacts dry eyes and mouth." (PMID 33917955, 2021).
encephalitis (1 paper, 2023). An acute inflammatory process affecting the brain parenchyma. "The serum of patients with LGI1 encephalitis had reduced levels of CD28, ICOS-L, PDCD1 (all p < 0.05), and CD86 (p < 0.01), but higher levels of ICOS (p < 0.05) and PD-L2 (p < 0.001) were detected." (PMID 37644514, 2023).
enteritis (1 paper, 2016). Inflammation of the small intestine. "Finally, the SBM-induced enteritis was associated with the transcriptomic activation of T cells by alteration of pathways related to CD28 signalling and CTLA4 signalling, as well as modification of the T cell receptor signalling pathway." (PMID 26925977, 2016).
epithelioid mesothelioma (1 paper, 2022). "In the xenograft model of epithelioid mesothelioma, BAFF-R- and TACI-based CAR T cells demonstrated equivalent tumor clearance to clinical benchmarks containing 4-1BB or CD28." (PMID 36350984, 2022).
generalized anxiety disorder (1 paper, 2023). An anxiety disorder characterized by excessive and difficult-to-control worry about a number of life situations. "By FDR correction (PFDR<0.05), we found two immunophenotypes to be protective against generalized anxiety disorder: CD24+CD27+B cells and CD28+CD4+T cells." (PMID 38264647, 2023).
glaucoma (1 paper, 2024). Increased pressure in the eyeball due to obstruction of the outflow of aqueous humor. "Interestingly, we found two members of the complement system central to the network describing GSE4316, CD28 and the TNF receptor superfamily member 9, TNFRSF9, but no entries about the involvement of these genes in glaucoma were found." (PMID 39458974, 2024).
glomerular disease (1 paper, 2020). "Anti-cytotoxic T-lymphocyte-associated protein 4 (CTLA4) immunoglobulin (Ig), which is able to block both activating CD28 and inhibitory CTLA4 signaling, has been shown in preclinical and clinical investigations to have effects on glomerular disease." (PMID 33251233, 2020).
Graves' orbitopathy (1 paper, 2015). "The present study was designed to investigate the expression of mRNA of the immune regulatory molecules FOXP3, CTLA-4/CD28/CD80/CD86, and CD40/CD40L in the orbital tissues from patients who underwent orbital decompression due to Graves' orbitopathy to assess their role in the inflammatory process." (PMID 25653477, 2015).
Headache (1 paper, 2022). Cephalgia, or pain sensed in various parts of the head, not confined to the area of distribution of any nerve. "Analyzing the side effects induced by the first dose of AZ vaccines, rs1879877 located in the promoter region of CD28 was found to be associated with headache (additive, p=0.009; GG+GT vs. TT, p=0.009, OR=18.75, 95% CI." (PMID 36389676, 2022).
hepatopathy (1 paper, 2022). "Staining for a corresponding CD127−PD-1highTIGIT+CD28+ population in a larger cohort of patients revealed that these cells were not expanded in patients with non-infectious diarrhea and/or hepatopathy as it is seen in patients without these complications." (PMID 35589883, 2022).
hidradenitis suppurativa (1 paper, 2026). A chronic suppurative and cicatricial disease of the apocrine glands occurring chiefly in the axillae in women and in the groin and anal regions in men. "We then apply it to Hidradenitis Suppurativa, comparing in vivo human lesions with ex vivo skin explants with and without CD3/CD28 stimulation, and show that stimulation selectively improves pathways that already recapitulate the human signal." (PMID 41838773, 2026).
hip fracture (1 paper, 2014). Traumatic or pathological injury to the hip in which the continuity of either the femoral head, femoral neck, intertrochanteric or subtrochanteric regions is broken. "On examining the additional effect of chronic stress on CD28 expression, a significant increase in the percentage of CD28-ve T cells was seen, especially in CD8 T cells in hip fracture patients with depressive symptoms." (PMID 25628751, 2014). "The majority of the CD57+ve T cells are also CD28-ve, therefore it is not surprising that an accumulation of CD28-veCD57+ve T cells was seen in hip fracture patients with depressive symptoms and this is in agreement with similar findings in depressed individuals." (PMID 25628751, 2014).
histiocytic sarcoma (1 paper, 2016). An aggressive malignant neoplasm with a poor response to therapy, usually presenting as stage III/IV disease. "It is unclear whether costimulatory molecules, including CD28, cytotoxic T-lymphocyte-associated antigen-4 (CTLA-4), and programmed death-1 (PD-1), are expressed on peripheral blood lymphocytes (PBLs) of canine patients with histiocytic sarcoma." (PMID 26901565, 2016). "The objective of this study was to evaluate the expression of CD28, CTLA-4, and PD-1 molecules on PBLs of patients with histiocytic sarcoma, patients with other tumors, and healthy controls." (PMID 26901565, 2016). "CD28, CTLA-4, and PD-1 expression levels were also compared between four dogs with localized histiocytic sarcoma and four dogs with disseminated histiocytic sarcoma in the histiocytic sarcoma group and five dogs with metastasis and five dogs without metastasis in the other tumor group." (PMID 26901565, 2016).
Huntington disease (1 paper, 2009). Huntington disease (HD) is a rare neurodegenerative disorder of the central nervous system characterized by unwanted choreatic movements, behavioral and psychiatric disturbances and dementia. "In contrast, for exclusive CoREST target genes, these pathways include CD28 signaling, chemokine signaling, glucocorticoid receptor signaling, and Huntington's disease signaling." (PMID 19997604, 2009).
Hypercholesterolemia (1 paper, 2010). An increased concentration of cholesterol in the blood. "At 4 weeks the immune response to an aggravated hypercholesterolemia was found to involve expression of IFN-γ by CD8+CD28+ T cells in plaque-draining lymph nodes and in the spleen." (PMID 21126329, 2010).
hypereosinophilic syndrome (1 paper, 2023). Hypereosinophilic syndrome (HES) constitutes a rare and heterogeneous group of disorders, defined as persistent and marked blood eosinophilia and/or tissue eosinophilia associated with a wide range of clinical manifestations reflecting eosinophil-induced tissue/organ damage. "Interestingly, the CD4+ Th2 cells found in a condition related to IgG4-RD and called “lymphocytic variant of human hypereosinophilic syndrome” are reminiscent of activated LatY136F CD4+ T cells in that they express low levels of TCR at their surface and primarily respond to CD28 signals." (PMID 37624388, 2023).
hypersensitivity pneumonitis (1 paper, 2025). Hypersensitivity pneumonitis (HP) is a pulmonary disease with symptoms of dyspnea and cough resulting from the inhalation of an antigen to which the subject has been previously sensitized. "In patients with fibrotic hypersensitivity pneumonitis, ozanimod alleviated CD3/CD28 induction of CD69, IL-4, and TNF in CD8, but not CD4 T cells." (PMID 40243992, 2025).
idiopathic inflammatory myopathies (1 paper, 2015). "Muscle-resident CD8+ T cells in idiopathic inflammatory myopathies are predominantly CD28 negative (CD8+CD28null) and IL-15 has been implicated in their generation." (PMID 26646698, 2015).
IgA nephropathy (1 paper, 2020). "The SNP of rs3181097 (-1059) in the promoter region of CD28 was related to the clinical pathology of childhood IgA nephropathy in Korean ethnic groups." (PMID 32210155, 2020).
IgG4-Related Disease (1 paper, 2022). "This study aimed to elucidate the changes and associated mechanisms of circulating CD28- cytotoxic T lymphocytes (CTLs) in patients with IgG4-related disease (IgG4-RD)." (PMID 35874706, 2022).
immune thrombocytopenia (1 paper, 2023). "Evidence thus far unanimously suggested stimulatory effects of Huaier or HQH on CD4+ T lymphocytes except for one study claiming that Huaier suppressed anti-CD3 and anti-CD28-induced PBMC activation and reduced IL-2 production of immune thrombocytopenia (ITP) patients." (PMID 37449208, 2023).
infectious mononucleosis (1 paper, 2025). A condition characterized by an increase in mononuclear white blood cells and swollen lymph nodes, which is usually caused by infection with the Epstein-Barr virus. "In summary, EBV-induced infectious mononucleosis is characterized by dysregulated expression of multiple immune markers in peripheral blood.The high expression of GzmB and low expression of CD28 are associated with LI in IM, and further mechanistic exploration is warranted." (PMID 41321447, 2025).
Intellectual disability (1 paper, 2018). "Several potentially pathologic genes within the deleted region were of interest including the intellectual disability gene SATB2 and the CD28/CTLA4/ICOS immune gene cluster." (PMID 30087679, 2018).
Interstitial pneumonitis (1 paper, 2005). "T-cell abnormalities in patients with ExRA include expansion of CD8+ large granular lymphocytes and of immunosenescent CD4+CD28- cells, and extensive CD4+ infiltrates in RA-associated interstitial pneumonitis." (PMID 16277691, 2005).
invasive candidiasis (1 paper, 2024). "Our previous study identified CD28+CD8+T cell-count as an independent risk factors for invasive candidiasis and early mortality in critically ill patients, which is consistent with the present study." (PMID 39726780, 2024).
Kaposi's sarcoma (1 paper, 2025). A malignant neoplasm characterized by a vascular proliferation which usually contains blunt endothelial cells. "Several chronic viral infections such as HIV, HCMV, EBV, hepatitis C virus, human parvovirus B19, Kaposi sarcoma as well as natural acute measles infection in children show increased populations of CD8+CD28− (CD8+CD57+) T-cells." (PMID 40431618, 2025).
laryngeal carcinoma (1 paper, 2017). Carcinoma that arises from the laryngeal epithelium. "The costimulatory signals CD28 and B7 have been shown to control tumor invasion and metastasis by regulating T cell activation, whereas the distribution characteristics of B7-associated proteins in laryngeal carcinoma (LC) tissue are still unclear." (PMID 29190910, 2017).
Lassa fever (1 paper, 2021). A viral hemorrhagic fever that is caused by the Lassa virus, which is transmitted by contact with infected rodents; it is characterized by fever, headache, malaise, myalgia, and hearing loss. "We assessed CD45RA, CD27, and CD28 levels to investigate the phenotypes of circulating effector/memory T cells induced during Lassa fever." (PMID 33398113, 2021).
leukoplakia (1 paper, 2021). A white patch or plaque on a mucous membrane that cannot be characterized clinically or pathologically as any other disease. "In addition, CYLD, CARD11, TCF7, CCR7, KLRB1, CD28, and ICOS were other significantly highly expressed genes among the proliferative leukoplakia subgroup (log2 fold changes, 0.65–3.51; all Padj = 0.001)." (PMID 36860910, 2021).
lymphedema (1 paper, 2018). Excess fluid collection in tissues, causing swelling. "On the basis of this knowledge, we then hypothesized that the absence of CD28 would prevent lymphedema, thus further confirming that TCR activation is necessary for disease development." (PMID 29773802, 2018). "Knowing this, we confirmed our hypothesis that CD4+ T cells must first be activated to promote lymphedema by demonstrating that the absence of the appropriate cognate antigen for the TCR or CD28 prevents the accumulation of the distinct inflammatory infiltrate seen in lymphedematous skin." (PMID 29773802, 2018).
lymphoid leukaemia (1 paper, 2024). "CD45RA+ CD28- CD8br AC mediated the causal relationship between Deoxycholic acid glucuronide and lymphoid leukaemia (Mediated proportion = -0.271%[-0.493%, -0.049%])." (PMID 39351228, 2024). "CD45RA- CD28- CD8br %T cell mediated the causal relationship between 1-stearoyl-2-linoleoyl-GPI (18:0/18:2) and lymphoid leukaemia (Mediated proportion = -8.31%[-15.7%,-0.872%])." (PMID 39351228, 2024).
lymphoid neoplasm (1 paper, 2021). A neoplasm composed of a lymphocytic cell population which is usually malignant (clonal) by molecular genetic and/or immunophenotypic analysis. "CD86 shows elevated expression in cluster 7 in comparison to the other clusters, which could not only indicate that CD86 is specific for lymphoid neoplasms, but also that the signaling pathway of CD86-CD28 is perturbed leading to CD28 stimulation." (PMID 34006939, 2021). "The lymphoid neoplasm samples in clusters 3 and 6 do not have an increased expression of both CD28 and CD86." (PMID 34006939, 2021).
mastitis (1 paper, 2024). Inflammation of breast tissue during lactation or postpartum due to an obstructed duct or infection. "Our results showed CD28- CD8dim %CD8dim immunophenotype was significantly linked to the risk of mastitis (p = 0.0006)." (PMID 39399489, 2024). "Consistent evidence supported the causal effects of CD28- CD8dim %CD8dim on mastitis across MR Egger (OR = 1.047, 95% CI = 1.013~ 1.082, p = 0.018), Weighted median (OR = 1.051, 95% CI = 1.013~ 1.090, p = 0.009) and Weighted mode methods (OR = 1.054, 95% CI = 1.017~ 1.092, p = 0.011)." (PMID 39399489, 2024). "And it was shown that CX3CL1, CD28- CD8dim %CD8dim and CD45 on CD33br HLA DR+ may suggestively be the upstream causes of mastitis, while heightened levels of CD39+ secreting Treg AC were connected to a reduced mastitis risk." (PMID 39399489, 2024). "Strikingly, elevated levels of CD28- CD8dim %CD8dim (OR = 1.058, 95% CI = 1.024 ~ 1.093, p = 0.0006) and CD45 on CD33br HLA DR+ (OR = 1.097, 95% CI = 1.039 ~ 1.157, p = 0.0008) could induce the risk of mastitis." (PMID 39399489, 2024). "Significantly, CD28- CD8dim %CD8dim (OR = 1.058, 95% CI = 1.024 ~ 1.093, p = 0.0006) and CD45 on CD33br HLA DR+ (OR = 1.097, 95% CI = 1.039 ~ 1.157, p = 0.0008) were found to induce mastitis possibly." (PMID 39399489, 2024).
Merkel cell carcinoma (1 paper, 2021). "We apply FAUST to data from a Merkel cell carcinoma anti-PD-1 trial and discover pre-treatment effector memory T cell correlates of outcome co-expressing PD-1, HLA-DR, and CD28." (PMID 34950900, 2021).
Miscarriage (1 paper, 2025). A pregnancy that ends at a stage in which the fetus is incapable of surviving on its own, defined as the spontaneous loss of a fetus before the 22th week of pregnancy. "In decidual tissues from human miscarriage, the mRNA expression of CD28 was increased, while the expression of CTLA-4 mRNA (the checkpoint marker) was decreased." (PMID 39941063, 2025). "Therefore, the ratios of CTLA-4+/CD28+ in miscarriage were significantly lower than in normal pregnancy, both in peripheral blood and the decidua." (PMID 39941063, 2025).
MRSA pneumonia (1 paper, 2017). "Recent results showed that T-cell signaling through CD28 contributes to MRSA pneumonia and that preventing T-cell co-stimulation significantly ameliorated the course of the disease in mice." (PMID 28264025, 2017).